BRAF (B-Raf proto-oncogene, serine/threonine kinase)
Diseases named in the same sentence as BRAF in open-access papers (continued):
Sharing a sentence is not in itself a finding about the gene and the disease.
melanoma (continued). "We also tested the effect of combined BRAF and ERK inhibition on BRAF-mutant melanoma in short-term and long-term cultures to determine if combination therapy would result in improved inhibition or delay the development of resistance in vitro." (PMID 25142146, 2014). "Another in vitro study examined how vemurafenib affects the ability of the TILs to recognize autologous BRAF(V600) mutant melanoma cell lines in vitro." (PMID 24743024, 2014). "Vemurafenib, but not MEK inhibitors, was therefore suggested as a preferable candidate for combination immunotherapy approaches in BRAF-mutant melanoma." (PMID 24743024, 2014). "In malignant melanoma activation of the BRAF-MEK-ERK and NFκB signaling pathways leads to induction of epithelial to mesenchymal transition (EMT) resulting in cell invasion." (PMID 24466036, 2014). "In melanoma cell lines, acquired BRAF inhibitor resistance is overcome by simultaneous MEK and PI3K/mTOR inhibition." (PMID 24970815, 2014). "The IC50 of SCH722984 or vemurafenib was next determined in eight BRAF-mutant vemurafenib-resistant melanoma cell lines." (PMID 25142146, 2014). "Phenformin, another antidiabetic drug that is no longer in use, also an AMPK activator, has a synergistic activity with vemurafenib in BRAF mutant melanoma in vitro and in vivo." (PMID 24743024, 2014). "Further, the development of drug resistance in BRAF V600E mutant melanomas can occur, often through MAPK reactivation, leaving a patient population with tumors that are in need of other effective therapeutic options." (PMID 25057921, 2014). "Here, we investigated the role of the ABC transporters ABCB1, ABCC1, and ABCG2 during melanoma cell resistance acquisition to the V600-mutant BRAF inhibitors PLX4032 (vemurafenib) and PLX4720." (PMID 25300205, 2014). "An example from the vemurafenib versus BRAF comparison is that one melanoma, LOXIMVI, although having the V600E alteration, has reduced sensitivity as compared to the other cell lines with that mutation." (PMID 25032700, 2014). "Alongside, we performed two shRNA screens on the same cell line to identify shRNAs that sensitize melanoma cells to targeted inhibition of either BRAF or one of its critical effectors, ERK (Fig1B; described in detail below)." (PMID 25538140, 2014). "In the majority of human melanomas, the mitogen-activated protein kinase (MAPK) pathway is constitutively activated by oncogenic mutations in NRAS or BRAF." (PMID 25422890, 2014). "In BRAF-mutated melanoma, ERK-dependent feedback suppress RAS activation and BRAF exists predominantly as an active monomer." (PMID 25344914, 2014). "Herein, we showed that combining the BRAF inhibitor dabrafenib with an AKTi potently inhibits growth in the majority of melanoma cell lines tested and induces cell death in a subset of cell lines." (PMID 24735930, 2014). "Eight cell lines including melanoma were assessed for their sensitivity to the BRAF, MEK, or RAF/MEK inhibitor using in vitro growth assays." (PMID 25422890, 2014). "To investigate if DCA can be used to improve the efficiency of chemical BRAF inhibitors for treatment of melanoma, we tested various combinations of DCA and vemurafenib on cellular growth." (PMID 25182332, 2014). "Independent research teams have identified three mechanisms by which melanoma can develop resistance to BRAF inhibitors." (PMID 24591764, 2014). "As in melanoma, the inhibition of oncogenic BRAF has been a major focus of these efforts in thyroid cancer, however the importance of additional pathways has been recognized." (PMID 24994118, 2014).
melanoma (continued). "The second is a double blinded randomized phase 3 study comparing trametinib and dabrafenib combination therapy to dabrafenib monotherapy in subjects with BRAF-mutant melanoma (ClinicalTrials.gov, NCT01584648)." (PMID 24693430, 2014). "The implications of RAS vs BRAF differential functions, in relevant tumour types including colorectal cancer, melanoma, lung cancer are discussed." (PMID 25361007, 2014). "There was a trend for unfavorable DMFS in patients with BRAF mutant vs. wild-type melanoma (p = 0.061)." (PMID 24475086, 2014). "We performed automated quantification of β-catenin immunohistochemical expression in pretreatment BRAF-mutant tumors from 32 BRAFi-treated melanoma patients." (PMID 24733413, 2014). "The driver mutations in BRAF and NRAS that have been identified cannot fully explain melanoma oncogenesis, as these same mutations have been found at similar rates in benign nevi, or moles." (PMID 25393105, 2014). "The oncogenic V600-mutant BRAF inhibitor PLX4032 (vemurafenib) caused improved response and survival rates in V600-mutant BRAF melanoma patients but PLX4032 resistance formation remains inevitable." (PMID 25300205, 2014). "Activity of mTORC1 after treatment of melanoma cells in vitro with BRAF or MEK inhibitors was found to be a faithful predictor of the response as evidenced by the phosphorylation status of ribosomal protein s6." (PMID 24743024, 2014). "Unprecedented clinical responses have been reported in advanced stage metastatic melanoma patients treated with targeted inhibitors of constitutively activated mutant BRAF, which is present in approximately half of all melanomas." (PMID 24733413, 2014). "Mutations in the BRAF gene occur in approximately 50% of melanomas, and multiple agents are now FDA-approved for the treatment of patients with BRAF-mutant metastatic melanoma (vemurafenib, dabrafenib and trametinib)." (PMID 29250602, 2014). "In contrast to mutBRAF melanomas, mutNRAS tumours are largely resistant to BRAF inhibitors, and moreover these drugs paradoxically stimulate the MAPK-pathway." (PMID 24941944, 2014). "For example, vemurafenib and dabrafenib are approved for the treatment of melanoma with BRAF V600E aberrations; trametinib is approved for melanoma with BRAF V600E or BRAF V600K aberrations." (PMID 25593991, 2014). "Fourteen NRAS mutant melanoma and seven cells lines with wild-type BRAF and NRAS were evaluated for SCH772984 sensitivity." (PMID 25142146, 2014). "Etnyre and colleagues reported that c-MET and BRAF inhibitors hadsynergistic inhibitory effects when exposed in combination to melanoma cell lines." (PMID 25490933, 2014). "Because the combination on BRAF combined with MEK inhibition is currently FDA approved for BRAFV600 mutant melanoma, we also determined the IC50 for the combination of vemurafenib and trametinib." (PMID 25142146, 2014). "A screen of 137 melanomas and 65 cell lines identified an activating mutation E17A in AKT1 (one patient) and AKT3 (one patient and two cell lines), all with concurrent BRAF mutations." (PMID 24743024, 2014). "HDACis combined with selective BRAF inhibitors synergistically induce cell death in BRAFV600E melanoma cells." (PMID 25521755, 2014). "Vemurafenib and dabrafenib are selective BRAF inhibitors that improve overall survival when compared with dacarbazine in patients with advanced, BRAF-mutant melanoma." (PMID 24983357, 2014). "Another BRAF inhibitor, dabrafenib has also been compared with dacarbazine in a phase 3 study of previously untreated advanced melanomas and this positive study showed an improvement in PFS, the study's primary endpoint." (PMID 24693430, 2014). "The histological analysis revealed a malignant melanoma, and BRAF molecular analysis of exon 15 codon 600 was performed by pyrosequencing analysis using the Pyromark 24 (Qiagen), according to the manufacturer’s instructions." (PMID 25120707, 2014).
melanoma (continued). "On the other hand, mutations in NRAS, a RAS family member and MEK1 have been shown to mediate acquired resistance to the mutant BRAF kinase inhibitor, vemurafenib, in melanoma cell lines." (PMID 25361007, 2014). "Combinations of targeted therapy and immunotherapy are ongoing in BRAF-mutant melanoma and currently involve the combination of BRAF inhibitors and ipilimumab, a monoclonal antibody targeting the cytotoxic T lymphocyte antigen-4 inhibitory receptor." (PMID 25594040, 2014). "It has been documented that activated MEK/ERK signaling in melanoma with mutant BRAF cells enhances cell proliferation and inhibits apoptosis." (PMID 25275294, 2014). "NF-1 was recently identified as top hit in an shRNA screen designed to identify genes whose disruption convey BRAF inhibitor resistance in melanomas." (PMID 24970815, 2014). "In a mouse model, NF1 ablation decreases the sensitivity of NF1 wild-type melanoma cell lines to BRAF inhibitors, and NF1 is lost in tumors from patients following treatment with these agents." (PMID 24743024, 2014). "To further explore the clinical relevance of DCA to melanoma treatment, we examined the efficacy of this agent in combination with the BRAF inhibitor vemurafenib." (PMID 25182332, 2014). "Advances in melanoma treatment through targeted inhibition of oncogenic BRAF are limited owing to the development of acquired resistance." (PMID 25182332, 2014). "Sensitivity of BRAF mutant melanoma cell lines to BRAFi predicted sensitivity to MEK and ERK inhibitors." (PMID 25142146, 2014). "Disruption of the RAF-MEK-ERK signaling with BRAF or MEK inhibitors has shown significant clinical responses in the treatment of melanoma, yet the rapid development of resistance to these inhibitors presents a formidable challenge." (PMID 25587028, 2014). "We also performed deep sequencing of somatic mutations that uncovered the clonal structures of melanomas, helped to dissect diverse mutational mechanisms in subclones, and further established the initiation roles of BRAF and NRAS mutations in melanoma." (PMID 25393105, 2014). "Their genetic and gene expression analyses revealed that Spry2 is downregulated in melanoma cells harboring WT BRAF yet upregulated in the BRAFV600E mutants." (PMID 24744103, 2014). "Promisingly, PLX 7904 inhibited ERK1/2 phosphorylation in mutant BRAF melanoma cells with acquired resistance to vemurafenib/PLX4720 that is mediated by a secondary mutation in NRAS." (PMID 24743024, 2014). "New targeted melanoma treatments, such as BRAF inhibitors, vemurafenib (PLX4032) and dabrafenib (GSK2118436) offer higher patient response rates due to specific BRAFV600 targeting." (PMID 25333256, 2014). "In our function-based and unbiased genomic approach, we employed two screens to identify factors whose targeted silencing sensitizes melanoma cells to BRAF pathway inhibition." (PMID 25538140, 2014). "If the primary melanoma was a cutaneous melanoma, mutation analysis of NRAS and BRAF can be of help, but since these mutations are hotspot mutations, it is of limited use." (PMID 25593912, 2014). "In melanoma, research on resistance to novel therapeutic options (such as BRAF inhibition) has resulted in identification of several molecular alterations that confer resistance." (PMID 24399611, 2014). "Our results extend the previous model for how Wnt/β-catenin and BRAF/MAPK signaling interact in melanoma." (PMID 24733413, 2014). "For instance, BRAF-mutant melanoma patients treated with BRAF inhibitors exhibit increased tumor infiltration by CD8+ lymphocytes early during therapy." (PMID 25594040, 2014).
melanoma (continued). "Recent therapeutic approaches including small molecule inhibitors of activated BRAF pathways (vemurafenib, dabrafenib) and immunomodulatory agents represent significant advances in melanoma therapy." (PMID 25057921, 2014). "In October 2011, the patient was enrolled to Expanded Access Program (MO25515) evaluating vemurafenib in patients with advanced BRAF-mutant melanoma." (PMID 25501056, 2014). "Genome MuSiC v0.4 is then used to investigate the presence of significantly mutated pathways, recurrent mutations, clinical correlations and mutation-relations between genes (such as mutual exclusivity of BRAF and NRAS mutations in melanoma)." (PMID 24752294, 2014). "Historically antifolate drugs such as methotrexate or edatrexate have shown very little activity in clinical trials with melanoma patients although these trials were performed before the discovery of BRAF and RAS as drivers of melanomagenesis." (PMID 24941944, 2014). "Our analysis of serial tumor biopsies in patients with BRAF-mutant melanoma treated with BRAFi has revealed a number of findings." (PMID 24983357, 2014). "Insulin receptor substrates 1 and 2 (IRS1/2) mediate oncogenic signaling from IGF-1R and are upregulated in melanoma cell lines resistant to BRAF inhibitors or derived from patients that developed resistance to vemurafenib treatment." (PMID 24743024, 2014). "This case supports recent studies, which showed a differential influence of different BRAF inhibitors on patients’ leukocytes despite similar clinical efficacy in melanoma." (PMID 25526431, 2014). "The role of glycolysis in responses of melanoma to mutant BRAF inhibition were highlighted in a study that demonstrated that concurrent inhibition of BRAF and glycolysis induces cell death in BRAF inhibitor-resistant melanoma cells." (PMID 24743024, 2014). "BCL2A1, a lineage-specific anti-apoptotic protein in the BCL2 family, is amplified and overexpressed in MITF-high melanomas, and confers resistance to BRAF inhibitor." (PMID 24743024, 2014). "It should be noted that in melanoma, BRAF and NRAS mutants can in some cases coexist in the same tumour in contrast with colorectal cancer." (PMID 25361007, 2014). "By combining our genomic data with (phospho)proteomic analyses, we were able to identify a new target, ROCK1, whose inhibition rendered melanoma cells much more sensitive to BRAF/MAPK inhibition." (PMID 25538140, 2014). "Using a cell proliferation assay, theyreported that fibroblast-conditioned medium rescued BRAF-mutant melanoma cells fromPLX4720 sensitivity, which indicated that a secreted factor was involved." (PMID 25490933, 2014). "PLX4032 and PLX4720 also sensitised two wild-type BRAF melanoma cell lines, IPC-298 and SK-Mel-30 (DSMZ, Braunschweig, Germany), that express ABCB1, ABCC1, and ABCG2 to vincristine and mitoxantrone." (PMID 25300205, 2014). "Pathways involved in cancer and related to BRAF activity, such as “Melanoma”, “MAPK”, “Pathways in cancer” were strongly enriched (fold enrichment of 2.35, 1.84, 2.06; p-value of 3e-7, 8e-11, 2e-20 respectively)." (PMID 25188415, 2014). "This combination therapy therefore appears a very promising treatment option for BRAF mutant melanomas and is likely to play a pivotal role in the treatment of this group of patients." (PMID 24693430, 2014). "The activation of MET and SRC signaling was detected in two patient-derived melanoma cell lines with BRAFV600E that were resistant to BRAF inhibitor PLX4032." (PMID 24743024, 2014). "Significantly mutated gene analysis using 13 WGS cases and 15 additional paired extension cases identified known melanoma genes such as BRAF, NRAS, and CDKN2A, as well as a novel gene EPHA3, previously implicated in other cancer types." (PMID 25393105, 2014). "Resistance to BRAFV600E inhibition in NSCLC involves some of the mechanisms previously encountered in BRAF mutant melanoma." (PMID 24722523, 2014).
melanoma (continued). "The affirmation of new drugs inhibiting some mediators of the MAPK pathway, including mutated BRAF and activated MEK, has led to major advances in the treatment of patients with melanoma." (PMID 24885594, 2014). "The use of BRAF inhibitors have transformed melanoma therapy however their use in brain tumors remains unproven." (PMID 24725538, 2014). "It is worth noting that the BRAF(V600E) melanoma cell lines with a PDGFRα up-regulation mediated BRAF-I resistance did not express PDGFRβ and VEGFR2." (PMID 24732172, 2014). "While the rate of BRAF mutant melanoma was 75% in patients younger than 30 years (n = 15) it was only 19% in patients aged 70 years or more (n = 84)." (PMID 24475086, 2014). "Usage is additionally hampered by frequent occurrence of heterogeneity in melanoma with respect to NRAS and BRAF status, leading to a substantial discordance in mutation status in these genes in a primary compared to the metastases." (PMID 25593912, 2014). "ROCK1 silencing increased melanoma cell elimination when combined with BRAF or ERK inhibitor treatment." (PMID 25538140, 2014). "M233 was among the resistant BRAFV600E melanoma cell lines, which appeared to have increased pAKT at baseline compared to other BRAF mutant cell lines." (PMID 25142146, 2014). "Being overexpressed in melanoma, the oncogenic BRAF-induced BANCR can regulate a set of genes involved in cell migration and is required for full migratory capacity of melanoma cells." (PMID 24967732, 2014). "Most importantly, it is increasingly clear that combination treatments, such as BRAF and MEK inhibition investigated in a recently reported clinical study, have potential for a robust and lasting clinical response in the treatment of BRAF-mutant melanoma." (PMID 24743024, 2014). "In this study, we aimed at assessing the frequency and distribution of alterations in candidate genes (BRAF, cKIT, CyclinD1) involved in pathogenesis of melanoma in a large series of patients with synchronous or asynchronous MPM lesions." (PMID 24885594, 2014). "There is evidence that oncogenic BRAF is immunosuppressive, and T cell infiltrates in BRAF-mutant melanomas are low prior to initiating therapy with a BRAFi." (PMID 29250602, 2014). "In a second report, from Rene Bernards and colleagues, a novel mechanism of resistance to BRAF inhibition in melanoma was described." (PMID 25031620, 2014). "Recent reports have confirmed that BRAF-inhibitor treated melanoma patients rapidly develop multiple, independent mechanisms of resistance that can exist within a single progressing tumor." (PMID 25594040, 2014). "The most serious adverse events noted in patients receiving dabrafenib include squamouscell carcinomas of the skin, tumor promotion in BRAF wild-type melanoma, serious febrile reactions,hyperglycemia, and uveitis/iritis." (PMID 25089220, 2014). "Actually, BRAF inhibition can induce the enhanced T cell recognition and subsequent T cell response on melanoma cells, and BRAF inhibitor vemurafenib improves the antitumor activity of ACT for advanced melanoma in mice." (PMID 25009822, 2014). "The effect of BRAF inhibition on anti-tumor immunity will be discussed herein, as will potential implications of these findings in the treatment of melanoma." (PMID 29250602, 2014). "17.8% of patients with BRAF mutant tumors but only 10.4% wild-type melanoma patients progressed to stage IV during observation (p = 0.031)." (PMID 24475086, 2014). "Here, I highlight two such recent studies that address the treatment of BRAF mutant melanoma, revealing new therapeutic strategies that can potentially improve outcomes for such patients." (PMID 25031620, 2014).